KIFC1 (kinesin family member C1)
Diseases named in the same sentence as KIFC1 in open-access papers (continued):
Sharing a sentence is not in itself a finding about the gene and the disease.
pancreatic cancer (5 papers, 2021 to 2025). "The presented data imply a possible association between KIFC1 expression and the malignant pathogenesis of pancreatic cancer." (PMID 38112634, 2023). "Our results demonstrated that KIFC1/2C/4A/11/14/15/18A/18B/20B/23 (we name it prognosis-related KIFs) were upregulated and associated with unfavorable clinical outcome in pancreatic cancer patients." (PMID 34557409, 2021). "High expression of KIFC1 was significantly associated with a poor prognosis of pancreatic cancer." (PMID 40612867, 2025). "Based on these results, it can be concluded that KIFC1 is essential for the development and progression of pancreatic cancer, and may be a diagnostic and therapeutic target." (PMID 40612867, 2025). "The area under the ROC curve was 0.631, with a specificity of 0.541 and a sensitivity of 0.674, suggesting that the expression of KIFC1 might be used as a diagnostic marker for pancreatic cancer." (PMID 40612867, 2025). "KIFC1 expression is closely associated with pancreatic cancer; however, the underlying mechanisms remain unclear." (PMID 40612867, 2025). "To further clarify the KIFC1 expression pattern, we determined its mRNA levels in the three pancreatic cancer cell lines." (PMID 40612867, 2025). "Univariate and multivariate Cox regression analyses demonstrated that pathological N and KIFC1 expression levels were independent prognostic factors of pancreatic cancer." (PMID 40612867, 2025). "Knockdown of KIFC1 suppresses the proliferation, migration, and invasion of pancreatic cancer cells and tumor growth in vivo." (PMID 40612867, 2025). "This is the first study to identify ETV1 as a transcriptional regulator of KIFC1 in pancreatic cancer cells." (PMID 40612867, 2025). "The present study clarified the tumor-promoting action of the KIFC1/ETV1 axis in pancreatic cancer by strengthening cell proliferation, migration, and invasion." (PMID 40612867, 2025). "Knockdown of KIFC1 suppressed the proliferation, migration, and invasion of pancreatic cancer cells and tumor growth." (PMID 40612867, 2025). "KIFC1 expression levels were determined by immunohistochemistry (IHC) in our pancreatic cancer cohort." (PMID 40612867, 2025). "The results from the analysis of the association between KIFC1 expression and clinical characteristics in pancreatic cancer showed that KIFC1 is relatively highly expressed in the higher age over 65 and histologic grade." (PMID 38112634, 2023). "Based on the previous findings of over-expression of KIFC1 correlated with poor survival expectations in patients with pancreatic cancer, we deeply mined the role of KIFC1 in the carcinogenesis of pancreatic cancer adenocarcinoma." (PMID 38112634, 2023). "We investigated the differential expression of KIFC1 in pancreatic cancer cell lines and HPDE by employing Western blot analysis." (PMID 38112634, 2023). "Through univariate and multivariate Cox regression analyses using TCGA data, KIFC1 was identified as an independent predictor of prognosis in pancreatic cancer cases." (PMID 38112634, 2023). "Based on these findings, we propose that KIFC1 holds promise as a prognostic and immunotherapeutic biomarker in diverse malignancies, potentially impacting the proliferation and metastasis of pancreatic cancer cells." (PMID 38112634, 2023).
pancreatic cancer (continued). "This study also emphasized the potential of KIFC1 expression as a predictive factor for patient outcomes in pancreatic cancer." (PMID 38112634, 2023). "In vitro Edu, colony formation, wound healing, and Transwell assay were done to elucidate the biological functions of KIFC1 in pancreatic cancer cells." (PMID 38112634, 2023). "Additionally, the KIFC1/ETV1 as novel targets to treat pancreatic cancer should be explore in clinical practice." (PMID 40612867, 2025). "The ETV1/KIFC1 axis was involved in the abnormal expression of EMT-associated proteins and induced the proliferation, invasion, and migration of pancreatic cancer cells, thereby contributing to the progression of pancreatic cancer." (PMID 40612867, 2025). "KIFC1 serves as a tumor activator in pancreatic cancer by promoting proliferation, migration, invasion, and tumor growth, which may be partly manipulated by ETV1." (PMID 40612867, 2025). "Therefore, the current study clarified the expression pattern of KIFC1 in pancreatic cancer tissue specimens and cell lines and explored its role in the proliferation, invasion, and migration of pancreatic cancer cells, as well as tumor growth in vivo." (PMID 40612867, 2025). "The expression of KIFC1 in pancreatic cancer was further verified in our cohort samples using IHC." (PMID 40612867, 2025). "Interestingly, our cellular experiments in pancreatic cancer cells proved that after ablation of KIFC1, the apoptosis biomarkers diminished." (PMID 38112634, 2023). "In vitro experiments further confirm the oncogenic role of KIFC1 in pancreatic cancer." (PMID 38112634, 2023). "Our previous study results demonstrate that KIFC1 may be a critical factor in the initiation and development of pancreatic cancer." (PMID 38112634, 2023). "However, the role of KIFC1 in pancreatic cancer remains largely unexplored." (PMID 40612867, 2025). "ETV1 overexpression reversed the role of KIFC1 knockdown in inhibiting the proliferation, invasion, migration, and EMT of pancreatic cancer cells and tumor growth in vivo." (PMID 40612867, 2025). "KIFC1 knockdown and ETV1 overexpression were used to determine the role of the ETV1/KIFC1 axis in cell proliferation, migration, invasion, and epithelial-mesenchymal transition (EMT) of pancreatic cancer cells in vitro and tumor growth in vivo." (PMID 40612867, 2025). "In addition, the knockdown of KIFC1 inhibited N-cadherin and Vimentin expression and promoted E-cadherin expression, indicating that KIFC1 knockdown suppressed the EMT capacity of pancreatic cancer cells." (PMID 40612867, 2025). "Additionally, KIFC1 depletion led to alterations in the expression of Vimentin, N-cadherin, Bcl-2, E-cadherin, and BAX, suggesting that KIFC1 may contribute to carcinogenesis and progression by influencing apoptosis in pancreatic cancer cells." (PMID 38112634, 2023). "KIFC1 mRNA was significantly increased in pancreatic cancer PANC-1 and ASPC-1 cells, however, not in pancreatic cancer BXPC-3 cells, compared to the control HPDE6-C7 cells." (PMID 40612867, 2025).
colorectal cancer (4 papers, 2021 to 2025). A primary or metastatic malignant neoplasm that affects the colon or rectum. "The survival of colorectal cancer patients with a high KIFC1 expression was also significantly decreased." (PMID 33397932, 2021).
Clear Cell Renal Cell Carcinoma (3 papers, 2023 to 2026). "In conclusion, our study identified KIFC1 as an independent prognostic factor in renal clear cell carcinoma, and the associated processes involved tumor proliferation and immune infiltration." (PMID 37789080, 2023). "In conclusion, we identified KIFC1 as an independent prognostic factor in renal clear cell carcinoma." (PMID 37789080, 2023). "The mRNA expression of KIFC1 was significantly higher in clear cell renal cell carcinoma than in healthy tissue; KIFC1 mRNA expression increased significantly with the increase of tumor grade." (PMID 37789080, 2023). "Further, we found that KIFC1 is an independent prognostic factor in renal clear cell carcinoma, implying that high expression of KIFC1 has an obvious prognostic value in patients with renal clear cell carcinoma." (PMID 37789080, 2023).
glioma (3 papers, 2021 to 2025). A benign or malignant brain and spinal cord tumor that arises from glial cells (astrocytes, oligodendrocytes, ependymal cells). "Importantly, previous studies reported that AIFM3, LDHD, LYNX1, SCN2B or TMEM56 were all negatively corelated with glioma, and GINS1, KIFC1, NUF2, NUSAP1 or TPX2 were both positively related to glioma progression." (PMID 33277782, 2021).
head and neck cancer (3 papers, 2024 to 2025). A primary or metastatic malignant neoplasm affecting the head and neck. "In head and neck carcinoma, KIFC1 has been identified as an'activato' of the Wnt/β‐catenin signalling pathway, promoting the development of head and neck squamous cell carcinoma." (PMID 40857057, 2025).
ovarian adenocarcinoma (3 papers, 2016 to 2024). An adenocarcinoma that arises from the ovary. "Collectively, these observations indicate robust KIFC1 overexpression in human ovarian adenocarcinoma and strong association of KIFC1 expression levels with clinical progression of the disease." (PMID 26992853, 2016). "Our In silico analyses showed that higher KIFC1 expression was associated with poor overall survival (OS) in serous ovarian adenocarcinoma (SOC) patients suggesting that an aggressive disease course in ovarian adenocarcinoma patients can be attributed to high KIFC1 levels." (PMID 26992853, 2016). "To this end, we performed immunoblotting to evaluate expression level of centrosome clustering protein KIFC1 in cell lysates obtained from the ovarian adenocarcinoma cells (KURAMOCHI, OVCAR3, OVSAHO and SKOV3)." (PMID 26992853, 2016). "Taken together our findings underscore that KIFC1 is a potential prognostic biomarker in ovarian adenocarcinomas wherein expression levels of KIFC1 may predict the course of disease aggressiveness." (PMID 26992853, 2016).
cervical cancer (2 papers, 2024 to 2025). A primary or metastatic malignant neoplasm involving the cervix. "High expression of KIFC1 protein is associated with poor overall survival (OS) in patients with cervical cancer." (PMID 40379626, 2025). "However, the specific biological functions and underlying molecular mechanisms of KIFC1 in cervical cancer remain poorly understood." (PMID 40379626, 2025). "To verify USP25 influences KIFC1 stability by mediating its deubiquitination, we assessed the interaction between KIFC1 protein and ubiquitin in cervical cancer (CCa) cells." (PMID 40379626, 2025). "We specifically focused on two human cervical cancer cell lines, HeLa (adenocarcinoma) and SiHa (squamous carcinoma), which exhibited the highest KIFC1 expression." (PMID 40379626, 2025). "In cervical cancer, KIFC1 expression levels are significantly elevated compared to adjacent normal tissues, as observed in tumor cohort databases." (PMID 40379626, 2025). "To explore whether USP25 facilitates the progression of cervical cancer (CCa) through modulating KIFC1, we investigated the effects of KIFC1 overexpression in CCa cells with suppressed USP25 expression." (PMID 40379626, 2025). "Collectively, our findings elucidate the previously unknown functions and mechanisms of the USP25/KIFC1/MYCBP signaling axis in CCa progression, underscoring KIFC1 as a promising therapeutic target for cervical cancer." (PMID 40379626, 2025). "The USP25/KIFC1/MYCBP signal axis detected by RT-PCR did not change the expression level of c-MYC mRNA, but affected the expression levels of c-MYC transcription targets CDK4, CDK2, cyclin D1 and cyclin E which these have been reported to be regulated by c-MYC transcription in cervical cancer." (PMID 40379626, 2025).
cholangiocarcinoma (2 papers, 2023 to 2024). A carcinoma that arises from the intrahepatic biliary tree (intrahepatic cholangiocarcinoma) or from the junction, or adjacent to the junction, of the right and left hepatic ducts (hilar cholangiocarcinoma). "The KIFC1 genetic alteration profiles exhibit those amplifications (>2.5%) in cholangiocarcinoma and ovarian epithelial tumors ranked among the best." (PMID 38112634, 2023).
esophageal cancer (2 papers, 2023 to 2025). A primary or metastatic malignant neoplasm involving the esophagus. "KIFC1 exhibits varying prognostic significance in different tumors; however, its role in esophageal cancer remains unreported." (PMID 37955677, 2023). "In order to investigate the mechanism through which KIFC1 promotes proliferation in esophageal carcinoma cells, we utilized the data from 82 ESCC cases in TCGA for analysis." (PMID 37955677, 2023). "However, within the context of esophageal cancer, the expression parameters of KIFC1 remain largely underexplored." (PMID 37955677, 2023).
Globozoospermia (2 papers, 2016 to 2022). Any structural anomaly of the acrosome resulting in a round sperm head. "In humans, reduced testicular KIFC1 expression has been associated to globozoospermia, a male infertility syndrome typified by the presence of round-headed spermatozoa lacking the acrosome." (PMID 35547823, 2022). "In order to provide evidence that the deficient expression of KIFC1 may be a true pathogenic factor for patients with globozoospermia, we performed a functional analysis by knocking down Kifc1 expression in vivo in mice." (PMID 27690105, 2016). "Western blots and immunohistochemistry were utilized to evaluate the expression levels of the KIFC1 protein and showed a concomitant decrease of KIFC1 protein in the testes of globozoospermia patients compared to obstructive azoospermia." (PMID 27690105, 2016). "RT-PCR analysis revealed that nine of the thirty globozoospermia samples had significantly reduced expression of KIFC1 mRNA compared with that in the obstructive azoospermia samples (p < 0.001)." (PMID 27690105, 2016). "Compared with the control group, H&E staining showed that sperm treated with the Kifc1 siRNA1 had irregularly shaped round heads similar to those seen in human globozoospermia." (PMID 27690105, 2016). "In order to investigate the function of KIFC1 in human acrosomogenesis, we examined specimens obtained from testicular biopsies of patients with globozoospermia and obstructive azoospermia, and compared the expression of KIFC1 in the testes of these patients." (PMID 27690105, 2016). "Previous studies have shown that the association of KIFC1 with Hrb (also known as hRIP or RAB) plays an important role in acrosomogenesis, and that homozygous deletion of the Hrb gene from mice results in globozoospermia." (PMID 27690105, 2016). "The normal presence of KIFC1 expression in the other twenty-one samples from patients with globozoospermia may be explained by other genes or environmental factors." (PMID 27690105, 2016). "Decreased KIFC1 expression was mainly observed in the testes of patients with globozoospermia at the spermatid stage, which may be useful for counseling and management of such patients." (PMID 27690105, 2016). "We revealed that the testicular level of KIFC1 mRNA in globozoospermia was significantly reduced compared with that in obstructive azoospermia, and the KIFC1 protein was barely detectable in testicular specimens in 30% (9 of 30) of patients with globozoospermia." (PMID 27690105, 2016). "However, the relationship between the decreased expression of KIFC1 and human globozoospermia remains largely unknown." (PMID 27690105, 2016). "Moreover, clarifying the biological function of KIFC1 may facilitate the development of approaches for patient counseling and management, especially in cases of globozoospermia." (PMID 27690105, 2016). "In contrast, the KIFC1 signal was absent or barely detectable in nine of thirty globozoospermia samples." (PMID 27690105, 2016). "In the present study, expression analysis of KIFC1 by RT-PCR, immunohistochemistry, and Western blotting showed that KIFC1 was absent or undetectable in the testicular tissues of 30% (9 of 30) of patients with globozoospermia." (PMID 27690105, 2016). "In our study, KIFC1 immunostaining was absent or hardly detectable in the round and elongating/elongated spermatids of testes from nine patients with globozoospermia." (PMID 27690105, 2016). "H&E and PNA staining confirmed that sperm in Kifc1 siRNA1-treated mice had irregularly shaped round heads with malformed acrosomes or no acrosomes at all, which was similar to human globozoospermia, and that the proportion of sperm with globozoospermic defects was increased markedly to 26.5%." (PMID 27690105, 2016).
liposarcoma (2 papers, 2007 to 2024). A usually painless malignant tumor that arises from adipose tissue. "Among the various subtypes of sarcoma, leiomyosarcoma (LMS) exhibited elevated transcriptional levels of KIFC1 compared to normal muscle tissue and dedifferentiated liposarcoma (DDLPS) also had higher KIFC1 transcriptional levels than adipocytes." (PMID 39387242, 2024). "Genes highly expressed in the dedifferentiated/pleomorphic liposarcomas included cell-cycle genes like CCNA2, CCNB2, CDC2, KIFC1, KIF23 and PTTG1, motility genes like AMFR, ANXA1, CKB, CNN2 and FN1 and homeostasis-related genes." (PMID 17359542, 2007).
metastatic disease (2 papers, 2014 to 2021). "KIFC1 expression not only increased with higher Gleason scores, tumor stages, and metastatic disease; high KIFC1 expression was also associated with lower recurrence-free survival in PCa patients as well as patients with other cancer types." (PMID 33760984, 2021).
ovarian tumors (2 papers, 2014 to 2016). "Our in silico analyses showed KIFC1 overexpression in human ovarian tumors (n = 1090) and its upregulation associated with tumor aggressiveness utilizing publically-available gene expression databases." (PMID 25028599, 2014). "KIFC1 expression was analyzed in ovarian tumors using publically-available databases." (PMID 25028599, 2014). "Ingenuity based network prediction algorithms combined with pre-established protein interaction networks uncovered several novel cell-cycle related partner genes on the basis of interconnectivity, illuminating the centrosome clustering independent agenda of KIFC1 in ovarian tumor progression." (PMID 25028599, 2014). "In addition, an in silico-guided mechanistic understanding of KIFC1 gene interactions have delineated pathways and protein interactions which illuminate previously unrecognized partners of this centrosome clustering molecule to unravel the biological behavior of ovarian tumors." (PMID 25028599, 2014).
renal cell carcinoma (2 papers, 2021 to 2023). "The silencing of KIFC1 inhibited cell proliferation and arrested the cell cycle at the G2/M phase in renal cell carcinoma (RCC)." (PMID 37547464, 2023).
sarcoma (2 papers, 2021 to 2024). A usually aggressive malignant neoplasm of the soft tissue or bone. "However, this study does have limitations, particularly the difficulty of assessing KIFC1's function across more than 100 distinct sarcoma subtypes due to their inherent heterogeneity." (PMID 39387242, 2024).